RB1 (RB transcriptional corepressor 1)
Diseases named in the same sentence as RB1 in open-access papers (continued):
Sharing a sentence is not in itself a finding about the gene and the disease.
cancer (continued). "In samples with RB1 truncating mutations in BLCA and other cancers with frequent RB1 truncating mutations (few have been identified in PRCA), RB1 but not NUDT15 expression was significantly decreased after excluding RB1‐CN‐deleted samples." (PMID 40904703, 2025). "PIEZO1-mediated silencing of the retinoblastoma gene Rb1 drives immunosuppressive myelopoiesis in cancer and infectious disease." (PMID 40454475, 2025). "In summary, our data show that RBness is not only a transcriptional phenocopy of RB1-defective cancers but that it also exhibits clinical characteristics and synthetic lethal vulnerabilities that are known correlates of RB1 defects." (PMID 40138429, 2025). "To investigate the distinct profile of RB1 deleted cancer cells, we performed single‐cell transcriptome analysis using a publicly available resource." (PMID 40904703, 2025). "A subset of these cancers, which we term as “RBness,” lack RB1 genomic defects and yet phenocopy the transcriptional profile of RB1-defective cancers." (PMID 40138429, 2025). "Genomic defects caused by truncating mutations or deletions in the Retinoblastoma tumor suppressor gene (RB1) are frequently observed in many cancer types leading to dysregulation of the RB pathway." (PMID 40138429, 2025). "Next, we evaluated the prognostic and predictive performance of RBNSig-core in 14 cancer types where RB1 defects were frequently observed." (PMID 40138429, 2025). "RBNSig-BC–predicted groups (low, no confidence, and high) showed a gene expression profile similar to that observed in the TCGA discovery data, with enrichment of RB1-defective cancers in RBNSig-BC–high group (OR = 4, P = 0.0016, Fisher’s exact test; fig." (PMID 40138429, 2025). "Other notable mutated cancer-related genes include PIK3CA (7%), CREBBP (6%), KMT2C (6%), KMT2D (6%), RB1 (5%), PTEN (5%), and FAT1 (5%), all of which are reported as “Tier 1” cancer-related gene mutations in the COSMIC Cancer Gene Census21." (PMID 40057511, 2025). "In advanced cancers, such as metastatic CRPC, RB1 loss is associated with phenotypic plasticity and aggressive clinical outcomes." (PMID 41023204, 2025). "Retinoblastoma (Rb1) is a gene that codes for a tumour suppressor protein involved in various types of cancer." (PMID 39845333, 2025).
cancer (continued). "The role of Aurora kinases in mitosis is critical, as their overexpression is often associated with poor prognosis in various cancers, including SCLC, where inactivation of the RB1 tumor suppressor gene is prevalent." (PMID 39858036, 2025). "In RB1-deficient NEPC tumors, up-regulation of ACSL4 (a key enzyme promoting lipid peroxidation and triggering ferroptosis) renders cancer cells susceptible to ferroptosis inducers." (PMID 40746825, 2025). "This work introduces a transcriptional phenocopy of RB1-defective cancers, called RBness, that identifies aggressive forms of cancers." (PMID 40138429, 2025). "This study not only proves this idea but also highlights unexpected roles of the RB1-PGAMs axis in the behavior of stem-like cancer cells and in the RB1-dependent differentiation control of myocytes and adipocytes." (PMID 40707487, 2025). "The cancer-associated genes PTEN (7%), KMT2C (7%), KMT2D (7%), RB1 (6%), and CREBBP (4%), were again among the 15 most frequently mutated and at similar frequencies as observed in CALGB 40603." (PMID 40057511, 2025). "To test association with chemotherapy, we divided the RBNSig-BC–high group into bona fide RB1-defective cancers and RBness cancers." (PMID 40138429, 2025). "This unique transcriptional control by RB1 proposes a specialized role for PGAMs in cancer metabolism distinct from other glycolytic enzymes." (PMID 40707487, 2025). "We next carried out gene set enrichment analysis (GSEA) to unearth any other types of common cancer that acquire lesser glycolytic phenotype due to downregulation of RB1." (PMID 40707487, 2025). "The evading of anti-growth signaling is also an important hallmark of cancer cells, and PTMs of PTEN, RB1 protein, and YAP/TAZ are important in the modulation of growth signaling." (PMID 39860065, 2025). "The DEGs associated with long-term FLCN knockdown showed the greatest enrichment in ‘Aberrant regulation of mitotic G1/S transition in cancer due to RB1 defects’, Reactome: R-HSA-9659787 ( > 100-fold enrichment and 7.65E-04 FDR correction applied)." (PMID 40133475, 2025). "While RB1 is extremely well studied in the context of cancer, its role in the nervous system and PD has also been explored, where it is essential for the survival of post-mitotic neurons." (PMID 41430078, 2025). "Given the clinical implications of RB1 status in cancer, a number of molecular signatures that define the functional state of RB1 have been proposed." (PMID 40138429, 2025).
cancer (continued). "Using our integrated single‐cell transcriptome data, we also identified common RB1 deletions and distinct evolutionary enrichment at the pan‐cancer level." (PMID 40904703, 2025). "A proteogenomic approach identifies a class of cancers (RBness) that phenocopies RB1-defective tumors." (PMID 40138429, 2025). "While these findings suggest a relationship between EZH2 and RB1 across various cancers, direct evidence of EZH2's role in regulating RB1 expression remains limited." (PMID 40070134, 2025). "INK4a encodes the p16INK4a protein, which normally blocks cancer by inhibiting oncogenic cyclin-dependent kinases 4 and 6 (CDK4/6) and activating the Retinoblastoma 1 (RB1) tumor suppressor." (PMID 40723291, 2025). "In particular, deletion of the RB1‐containing region predominates over RB1 truncating mutations, and is the most prevalent deletion in PRCA according to the TCGA database and independent PRCA cohorts and other cancer types in Chinese patients." (PMID 40904703, 2025). "The effect of PRMT5 inhibition on blocking the G1-to-S transition in RB1-deleted cells suggests a potential approach to suppress cancer cell proliferation." (PMID 38480701, 2024). "In summary, these findings deepen our understanding of RB1 biology in cancer and provide a foundation for the rational design of targeted therapeutic approaches." (PMID 38672640, 2024). "Among the common groups of cancer mutations are those involving DNA damage repair (DDR) genes, DNA mismatch repair (MMR) genes, PTEN, FGFR, and RB1." (PMID 39590142, 2024). "Dysregulation or deletion in RB1 contributes to the development and progression of various cancers, making it a prime target for therapeutic intervention." (PMID 38672640, 2024). "The research summarized above details the multifaceted role of RB1 in cancer biology and its implications for targeted therapy." (PMID 38672640, 2024). "Differentially expressed genes from long-term FLCN knockdown showed greatest enrichment in ‘Aberrant regulation of mitotic G1/S transition in cancer due to RB1 defects’, Reactome: R-HSA-9659787 (> 100 fold enrichment and 7.65E-04 FDR correction applied)." (PMID 38978568, 2024). "The product of the Rb1 gene hinders the progression of the G1 to S phase in the cell cycle, restricting the proliferation of malignant cells, stopping cancer progression." (PMID 38778291, 2024). "The CDK–cyclin–Rb1 signaling pathway predominantly orchestrates the G1-to-S-phase transition in the cell cycle of cancer cells." (PMID 38474202, 2024). "Studies in RB1-defective cancer cells demonstrated the high sensitivity of these cells to Poly-ADP-Polymerase1,2 inhibitors (PARPi)." (PMID 38744935, 2024). "Recent investigations reveal that ncRNAs play intricate roles in modulating RB1 signaling, contributing to the complex landscape of cancer progression." (PMID 38279330, 2024). "Inactivating human Tsc2 in cancer cells inhibits RB1 mutant cell growth, indicating potential therapeutic strategies for RB1-inactivated cancers." (PMID 39000021, 2024).
cancer (continued). "REST (RE1 silencing transcription factor) and RB1 expressions are both downregulated by Interleukin 6 in cancer cells." (PMID 39480826, 2024). "Overall, we showed that NFYC-AS1 is an optimal candidate to be evaluated in the long term as a new target entity in different cancer types, including the very aggressive RB1-mut tumors." (PMID 38467619, 2024). "D-type cyclins activate CDK4 and CDK6, which subsequently phosphorylate and inactivate the RB1 tumor suppressor, thereby derepressing cancer cell proliferation." (PMID 39664374, 2024). "E2F3, a member of the E2F transcription factor family, is considered a transcriptional activator, is regulated by the RB1 protein, and is frequently overexpressed in cancer." (PMID 38920989, 2024). "The retinoblastoma (RB) transcriptional corepressor 1 (RB1) is a critical tumor suppressor gene, governing diverse cellular processes implicated in cancer biology." (PMID 38672640, 2024). "This review underscores the pivotal role of RB1 in cancer research and highlights its potential as a focal point for personalized therapies." (PMID 38672640, 2024). "Because RB1 is a major downstream effector of CDK4/6 signaling, RB1 loss in cancer cells contributes intrinsic resistance to CDK4/6i1,10–14." (PMID 38424044, 2024). "Hypermethylation of cancer suppressor genes such as RB1, CDKN2A, MLH1, VHL, and BRCA1, leading to their repression, has been observed in various cancer types." (PMID 38970307, 2024). "This review summarizes the multifaceted role of RB1 in cancer biology and its implications for targeted therapy." (PMID 38672640, 2024). "P16INK4A expression is inversely associated with RB1 expression in cancer cells, and P16INK4A inhibits CDK4-catalyzed RB1 phosphorylation." (PMID 39351198, 2024). "We found that NFYC-AS1 depletion by either ASOs or CRISPR/Cas9 results in cell growth impairment in both RB1-wt and -mut cancer cells, mainly due to downregulation of G2/M cell cycle phase genes." (PMID 38467619, 2024). "The clinical relevance of the RB1/E2F3a onco-spliceosome signature underscores its prognostic significance across various cancer types." (PMID 38672640, 2024). "The phosphorylation of some well-known cancer driver genes, including RB1 at T373, CDK1 at T161, and MCM at S27, has been identified exclusively in tumors." (PMID 39039072, 2024). "It regulates cell cycle entry forming, together with CDK6 and one of the three D-type cyclins (D1, D2, and D3), the G1-S transition promoter complex that phosphorylates critical substrates, such as RB1, and promotes excessive cell proliferation in cancer." (PMID 36769158, 2023). "The effect of PRMT5 inhibition on blockade of the G1-to-S transition in RB1-deleted cells suggested a novel approach to suppress cancer cell proliferation." (PMID 37502925, 2023). "RB1 is an immune-related prognostic biomarker and a promising target for immunotherapy in several cancers, including BLCA." (PMID 37324016, 2023).
cancer (continued). "RB1 disruptions sensitize cancer cells to ferroptosis in cancer cell types across various histological origins." (PMID 36928314, 2023). "It has been shown that SMYD2-dependent methylation of RB1 at K810 promotes cell cycle progression in cancer cells." (PMID 37894343, 2023). "Inactivation of the RB1 tumor suppressor gene is common in several types of therapy-resistant cancers, including metastatic castration-resistant prostate cancer, and predicts poor clinical outcomes." (PMID 36928314, 2023). "Inactivation of RB1 is widely present in multiple types of malignant tumors, including prostate, lung, and breast cancers." (PMID 38001596, 2023). "In particular, the targeting of cell cycle progression has advanced greatly with the development of CDK4/6 inhibitors that are now in clinical use for HER2+ breast cancer and are under investigation for the treatment of a variety of Rb1+ cancers." (PMID 37484531, 2023). "RB1 regulates G1 and S phases of the cancer cell cycle and interacts with the E2F transcription factor." (PMID 37903125, 2023). "In this study, we demonstrate that RB1 disruptions enhance ferroptosis in cancer cell lines of various histological origins." (PMID 36928314, 2023). "Some of the genes encompassed by these CNAs are known cancer genes and have been previously associated with OS pathogenesis, such as MYC, RB1, and RECQL4." (PMID 37445641, 2023). "Genomics and transcriptomics analysis of cancer patients reveal that RB1 alterations predict poor clinical outcomes, raising the need for targeted therapies." (PMID 37704395, 2023). "The deregulated E2F activity induced by the functional inactivation of RB Transcriptional Corepressor 1 (RB1) was found to be associated with aberrant cell proliferation and other cancer-related biological processes in various human cancers." (PMID 36855110, 2023). "RB1 is an important regulator of the cell cycle, and functional inactivation of RB1 has been recognized to occur in multiple human cancers, including TNBC." (PMID 37937640, 2023). "Endoplasmic reticulum and related structures are prominent amongst enriched CCs, and ‘aberrant regulation of the G1/S phase in cancer due to RB1 defects’ stands out as an enriched BPW." (PMID 36831729, 2023). "In 1986, RB1 was the first cancer gene to be cloned, improving our understanding of the genetic basis of cancer." (PMID 36479934, 2023). "The interplay between IFN-β and RB1 acts as a mechanism of cell cycle-based, tumor suppressor protein-mediated anti-cancer surveillance that can selectively suppress solid tumor or proliferating transformed cells from the loss of control leading to cancer." (PMID 37182173, 2023).